CXCR2 (C-X-C motif chemokine receptor 2)
Diseases named in the same sentence as CXCR2 in open-access papers (continued):
Sharing a sentence is not in itself a finding about the gene and the disease.
breast cancer (continued). "The breast carcinoma specific OVS and DFS were significantly shorter in the group of patients carrying CXCR2 (+1208) T allele." (PMID 20540789, 2010). "In the current study, we investigated the susceptibility and prognostic implications of the genetic variation in CXCR2 in breast carcinoma." (PMID 20540789, 2010). "Taken together, our findings elucidate a novel mechanism of IL8 signaling and identify Shp1 as a promising therapeutic target, highlighting the potential of modulating the CXCR2-Shp1 axis to limit invasiveness and metastasis in aggressive breast cancer subtypes, particularly TNBC." (PMID 41771840, 2026). "Some studies have indicated that tumor-secreted CCL20 activates granulocyte–monocyte progenitor cell differentiation through its receptor CCR6, leading to the expansion of PMN-MDSCs, which activates the CXCR2/NOTCH1/HEY1 signaling pathway to increase ALDH+ breast cancer tumor stem cells." (PMID 40722739, 2025). "Depression activates CXCR2-mediated breast cancer cell proliferation through IL-8, and senkyunolide H regulates CXCR2 and inhibits its ability to block the cancer-promoting effects of depression, ultimately inhibiting the growth of breast cancer in the context of depression." (PMID 40839237, 2025). "Further research indicated that CXCR2 could promote breast cancer chemoresistance by inhibiting AKT1 signaling and activating COX2 signaling." (PMID 39394189, 2024). "Organotypic microfluidic assays have shown that breast cancer cells do not exhibit extravasation dynamics into the muscle microenvironment, but do so into bone, through the interplay of breast cancer cell receptor CXCR2 and the chemokine CXCL5 secreted by the bone." (PMID 39439549, 2024). "For example, CXCL1 could accelerate the immune escape of breast cancer and non‐small cell lung cancer by recruiting CXCR2+ Tregs to establish immunosuppressive TME." (PMID 39051750, 2024). "Therefore, this study highlights the potential therapeutic value of targeting the CXCR2 or CCR2 pathway as a novel strategy to combat paclitaxel-resistant breast cancer." (PMID 37821959, 2023). "Furthermore, KT inhibits CXCL5 and CXCR2 expression, suppressing the secondary growth of breast cancer cells on the bone, brain, and lungs." (PMID 36674719, 2023). "We speculated that the enrichment of ALDH+ BCSCs induced by CXCL2 might contribute to the increased CXCR2 expression, which provided a positive feedback loop to promote the stemness of breast cancer cells." (PMID 36859354, 2023). "CXCR2-associated chemokines secreted by KDM2A-expressing CAFs stimulated M2 macrophage polarization, which in turn secreted CCL2 to increase paclitaxel resistance in breast cancer cells by activating CCR2 signaling." (PMID 37821959, 2023). "We have demonstrated the mechanisms by which CXCR2 signaling could modulate the spatio-temporal dynamics of the neutrophil responses toward brain-tropic breast cancers." (PMID 35158784, 2022). "Chemokine receptor 2 (CXCR2) is a typical G protein–coupled cell surface chemokine receptor, which has been found to be highly expressed in various cancers, including breast cancer." (PMID 35517812, 2022). "Interestingly, it has been reported that chemotherapy upregulates CXCR2 expression levels in breast cancer cells to increase its aggressiveness." (PMID 35517812, 2022). "Contrasting results were reported regarding the role of CXCR2 in breast cancer." (PMID 35158948, 2022). "However, metastatic breast cancer cells are known to induce metastasis supporting NETs and it has also been reported that CXCR2 agonists within TIME are the major mediators of tumor-induced NETs." (PMID 35158784, 2022). "In breast cancer, inhibition of CXCR2 increases the efficacy of chemotherapy." (PMID 33996815, 2021). "CXCR2 antagonism was tested in combination with immunotherapy consisting of adenovirus encoded TNF-related apoptosis ligand (TRAIL) plus TLR9 agonist, CpG, oligonucleotide (AdT + CpG) in a murine model of breast cancer." (PMID 34944914, 2021).
breast cancer (continued). "We could demonstrate that Cxcr2 is involved in the control of breast cancer development through the modulation of neutrophil composition within the primary tumor." (PMID 34070438, 2021). "CXCR2 (IL-8 receptor) is expressed on MDSCs, neutrophils, lymphocytes, and breast cancer cells." (PMID 33747948, 2021). "The addition of exogenous recombinant CXCL5 protein could promote the proliferation of quiescent breast cancer cells under healthy bone co-cultures via binding to CXCR2." (PMID 33771156, 2021). "Furthermore, myeloid-specific CXCR2 KO mice displayed decreased intra-tumor infiltration of MDSCs both in models of breast cancer and melanoma, and those remaining MDSCs were less functional." (PMID 34944914, 2021). "Consequently, targeting the CXCL8-CXCR1/CXCR2 axis has been adopted as a breast cancer therapy strategy." (PMID 33747948, 2021). "CXCR2 can facilitate breast cancer metastasis and chemoresistance and gastric cancer metastasis." (PMID 33336008, 2020). "Also, it has reported that CXCR2+ MDSCs promote breast cancer growth and metastasis via inducing cancer cell EMT thus promoting T cells exhaustion." (PMID 32596152, 2020). "This is in contrast to metastatic breast cancer models that show G-MDSCs infiltrating tumors and driving metastasis; where in those cases we would hypothesize that CXCR2 or another MIF receptor may play a more vital role." (PMID 32625208, 2020). "We hypothesized that CXCR2 expression could be also altered in breast cancer and could account for a differential recruitment in the tumor microenvironment." (PMID 32727083, 2020). "Furthermore, CXCR2 and several of its ligands (CXCL1, CXCL2, CXCL5, CXCL7 and CXCL8) have also been linked to breast cancer progression and metastatic invasion." (PMID 32581213, 2020). "CXCR2, CD11b and CD66b expression were correlated with high grade breast cancers." (PMID 32727083, 2020). "Prostaglandin-endoperoxide synthase 2 (PTGS2) might mediate the CXCR2 signaling to inversely control the breast cancer metastasis and chemoresistance through the regulation of EMT, apoptosis, and senescence." (PMID 33708105, 2020). "In accordance with our results, researches have demonstrated that CXCR2+ MDSCs were predominately expanded and recruited in breast cancer and could boost EMT of breast cancer cells dependently on IL-6/STAT3 signaling." (PMID 32092078, 2020). "Lastly, to determine whether host Cxcr2 status can influence the mammary tumor cell bone metastasis, we injected Cl66-Luc cells intracardially in the wild type and Cxcr2−/− mice and monitored the spread of tumor cells in real time." (PMID 30871004, 2019). "However, there is minimal literature investigating the role of CXCR2 in bone metastasis of breast cancer." (PMID 30871004, 2019). "To determine the role of CXCR2 signaling in the tumor-bone interface, we utilized an experimental osteolytic bone metastasis model; implanting the breast cancer cells on the dorsal calvaria of mice and evaluating the tumor growth, bone destruction index, and osteoclast activation." (PMID 30871004, 2019). "CXCR2 binds to all these chemokines, which have been shown to promote metastasis in various cancer types, and this appeared to us as a promising molecule to study to assess bone metastasis in breast cancer." (PMID 30871004, 2019). "In this study, we tested the hypothesis that CXCR2 contributes to mammary tumor-induced osteolysis and bone metastasis." (PMID 30871004, 2019). "In addition, CXCL1, a cognate ligand of CXCR2, has also been reported to promote metastasis of breast cancer via CXCR2." (PMID 31390756, 2019). "However, findings from tumor research show that CXCL8 stimulation upregulates CXCR4 levels in prostate carcinoma cells and CXCR4 drives tumor invasion and metastasis via activating CXCR2 in breast cancer." (PMID 31885605, 2019).
breast cancer (continued). "Also, we observed a similar reduction in tumor growth and osteolysis in CXCR2 knockout mice injected with murine breast cancer cells than in the wild type Control mice." (PMID 30871004, 2019). "And CXCR2+ MDSCs exhibited a high proportion in peripheral blood, bone marrow, spleens and tumor tissues derived from every tumor-bearing mouse on day 35 after breast cancer cells inoculation." (PMID 29383101, 2017). "CXCL1/2-CXCR2 axis may involve in breast cancer progression, and Ly6G+CD11b+ cells sorted from tumor tissues express higher levels of CXCR2 than Ly6C+CD11b+ cells, F4/80+ cells and CD31+ cells." (PMID 29383101, 2017). "In this study, we focus on the function of CXCR2+ MDSCs in breast cancer progression." (PMID 29383101, 2017). "Furthermore, CXCR2+ MDSC subsets induced breast cancer cells epithelial mesenchymal transition (EMT) via IL-6." (PMID 29383101, 2017). "Besides, CXCR2+ MDSCs promote breast cancer growth and metastasis to lung and/or lymph node in vivo." (PMID 29383101, 2017). "Similarly, kruppel-like factor KLF4 regulates the recruitment of MDSCs to primary tumor via CXCL5/CXCR2 axis in breast cancer model." (PMID 29383101, 2017). "CXCR2+ MDSCs could expand and recruit during breast cancer progression, and promoted primary cancer cells metastasize to lung or lymph node." (PMID 29383101, 2017). "Furthermore, CXCR2+ MDSCs induce epithelial mesenchymal transition (EMT) of breast cancer cells via IL-6." (PMID 29383101, 2017). "Collectively, these results demonstrated that CXCR2+ MDSCs could promote breast cancer progression and metastasis." (PMID 29383101, 2017). "Blockade of the CXCR2 signaling pathway can significantly enhance the effect of chemotherapy in colon cancer patients and inhibit the proliferation and invasion of chemotherapy-resistant breast cancer cells." (PMID 29312644, 2017). "Here, we identify that CD45+Ly6GmiLy6CloCD11b+ subpopulation are predominately expanded and recruited in systemic and local tumor microenvironment during breast cancer progression and metastasis, which expresses CXCR2 at high proportion, then we named this subset CXCR2+ MDSCs." (PMID 29383101, 2017). "Therefore, we detected IL-6 secretion in the supernatant of co-culture medium of breast cancer cells and CXCR2+ MDSCs." (PMID 29383101, 2017). "Next, we want to explore whether CXCR2+ MDSCs promote breast cancer progression and metastasis in vitro and in vivo." (PMID 29383101, 2017). "Here, we found that CXCR2+ MDSCs could reshape breast cancer cells to mesenchymal-like via boosting EMT." (PMID 29383101, 2017). "Furthermore, the expansion of CXCR2+ MDSCs in peripheral blood and spleens was in a time-dependent manner during breast cancer progression." (PMID 29383101, 2017). "In addition, our previous study has shown that TFF3 promotes STAT3-dependent transcription of IL8, thereby stimulating angiogenesis in mammary carcinoma through the IL-8/CXCR2 axis." (PMID 29100386, 2017). "We demonstrate that the induced migration of a2Neuɸ is hampered significantly by anti-IL-8 neutralizing monoclonal antibody as well as by reparixin; a CXCR-1 and CXCR-2 inhibitor that is used in phase 2 clinical trial for Triple negative breast cancer treatment." (PMID 27845385, 2016). "Recent studies have shown that CXCL1/2 can be hyperactivated in breast cancer cell lines by chemotherapy and that blocking CXCR2 in conjunction with chemotherapeutic agents could markedly reduce lung metastases in xenograft-implanted mice." (PMID 26503598, 2015). "In vivo studies showed that CxcR2 signaling significantly contributed to enhanced metastasisobserved from the TGF-β1 signaling deficient mammary carcinoma cell population, when compared with the control mammary carcinoma cells." (PMID 24891760, 2014). "Taken together, these data would support that the CXCL7/CXCR2 axis may be important in breast cancer metastasis." (PMID 20652010, 2010).
breast cancer (continued). "The CXCR2 gene polymorphisms were associated with pancreatic cancer but not with prostate and breast cancer." (PMID 20540789, 2010). "Then we used existing and additional genotype data on 409 breast cancer cases and 301 healthy controls to examine the potential contribution of the combined genotypes of IL-8 and CXCR2 in breast carcinoma occurrence, clinico-pathological characteristics and prognosis." (PMID 20540789, 2010). "Previous work in our laboratory showed that breast cancer cells coexpress CXCL7 and CXCR2, which may act as a potential autocrine mechanism in breast cancer." (PMID 20652010, 2010). "Additionally, CXCL1 could facilitate PMN formation in breast cancer and colorectal cancer by recruiting CXCR2+ MDSCs." (PMID 39051750, 2024). "Therefore, blocking the CXCL8-CXCR1/2 axis by using small molecules or antibodies were testes, such as SB225002 (CXCL8 inhibitor binding to CXCR2) to inhibit tumor progression in HER2+ breast cancer, and danirixin (GSK1325756) to suppress cancer migration, invasion, and metastasis." (PMID 36835413, 2023). "Furthermore, flow cytometry results show that the population of CD11b+GR1+-MDSCs in the spleen, lung, and peripheral blood of CXCR2KO mice was significantly reduced, further confirming the crucial role of CXCL1/CXCR2 axis in regulating the bio-functions of MDSCs during breast cancer progression." (PMID 37210553, 2023). "It is widely accepted that CXCR1 and CXCR2 are essential for the initiation and growth of human tumors, thus serve as the novel therapeutic targets for many solid tumors, including lung cancer, breast cancer, prostate cancer, ovarian cancer, liver cancer and melanoma." (PMID 35768814, 2022). "Using ex-vivo co-culture systems of breast cancer cells and mouse bones, others have also shown that a CXCL5/CXCR2 (the IL-8 receptor-β) signaling axis might be involved in regulating the balance between cancer cell quiescence/dormancy and subsequent breast cancer outgrowth in bone." (PMID 33809315, 2021). "Furthermore, CXCL5 can recruit MDSCs to the tumor via CXCR2 and promote breast cancer progression." (PMID 34439836, 2021). "Our hypothesis was that CXCR2 expression could also be altered in breast cancer." (PMID 32727083, 2020). "Interestingly, CXCR2 could be also a potential cancer stem-like cell marker, as a costaining of some breast cancer cells with NANOG and SOX2 has been reported and also that CXCR1/2 inhibition decreases mammosphere formation." (PMID 32727083, 2020). "In addition, the chemokines (e.g., growth-regulated protein beta (Gro-β), interleukin 8 (IL-8)) produced by endothelial cells could stimulate invasiveness of breast cancer cells highly expressing c-x-c motif chemokine receptor 2 (CXCR2)." (PMID 32180051, 2020). "However, CXCR2 can affect different signaling pathways, and more investigations are needed to define the major signaling pathways affected upon CXCR2 depletion in mammary tumor-induced bone destruction, growth and metastasis." (PMID 30871004, 2019). "CXCR2 blocking with small molecular antagonists or receptor antagonists could have therapeutic importance in reducing the metastatic disease progression in breast cancer." (PMID 30871004, 2019). "Therefore, the CXCL5/CXCR2 axis may be physiologically relevant to human patients affected by metastatic disease to the bones from breast cancer." (PMID 31562303, 2019). "Moreover, in a mouse model of breast cancer lung metastasis, MSCs that were pre-conditioned with TNFα and co-injected with tumor cells were shown to recruit CXCR2+ neutrophils by secreting CXCR2 ligands (CXCL1, CXCL2, and CXCL5), resulting in enhanced lung metastasis." (PMID 31428105, 2019). "Previous studies have confirmed that CXCR2+neutrophils are mainly observed in the stroma, where they play critical roles in mediating angiogenic activity, lymph node metastasis, and tumour proliferation in colon cancer, oral squamous cell cancer, oesophageal cancer, and breast cancer." (PMID 29661142, 2018).
breast cancer (continued). "Furthermore, IHC analysis of 1° IRISOE orthotopic mammary tumor confirmed that high-level CXCR2 could be observed on the surface of tumor cells only." (PMID 29262555, 2017). "CXCR2+ MDSCs could promote breast cancer growth and metastasis to lung and/or lymph node in vivo." (PMID 29383101, 2017). "Moreover, CXCR2+ MDSCs could induce breast cancer cells EMT via IL-6, and promote activated CD4+ or CD8+ T cells exhaustion partially via IFN-γ." (PMID 29383101, 2017). "Then, whether CXCR2+ MDSCs could promote breast cancer cells EMT needed to be investigated." (PMID 29383101, 2017). "Moreover, depletion of CXCR2 has been shown to alleviate the metastatic abilities of melanoma and metastatic breast cancer cells, but how CXCR2 could play different roles in different cancer cells remains unclear." (PMID 22789011, 2012). "In breast cancer, the role of CXCR2 in cancer development and metastasis remains unclear." (PMID 22789011, 2012). "On this basis, we found that senkyunolide H binds to CXCR2, inhibits the activation of CXCR2 by inflammatory factors (such as IL-8 and CXCL1), and blocks the pro-breast cancer effect of depression." (PMID 40839237, 2025). "In breast cancer, specific inflammatory signaling cascades – including the NF-κB, JAK-STAT, PI3K-Akt, TGF-β, and CXCR2 pathways – govern neutrophil behavior, modulating immune suppression, angiogenesis, metastasis, and therapy resistance." (PMID 40486614, 2025). "Specifically, in breast cancer, the chemokine receptors that exhibited the most significant correlations were CCR2, CCR4, CCR5, CCR6, CCR8, CXCR2, and CX3CR1." (PMID 40649753, 2025). "Biomarkers like CXCR2, CD66b, and NLR have emerged as valuable tools to better understand the dynamics of neutrophil behavior in breast cancer and to guide treatment decisions." (PMID 40486614, 2025). "We demonstrated that the tumor CXCR2-mediated PI3K/AKT signaling pathway is activated during depression, thus promoting breast cancer cell proliferation." (PMID 40839237, 2025). "The exploration of biomarkers such as CXCR2, CD66b, and NLR holds significant promise for improving breast cancer treatment." (PMID 40486614, 2025). "CCL20-regulated PMN-MDSCs secrete large amounts of CXCL1 by binding to CXCR2 and activating the NOTCH1/HEY2 signaling pathway in BC cells, leading to an increase in breast cancer stem cells (BCSCs)." (PMID 38609997, 2024). "SRGN is an activator of CXCR-2 pathway by regulating the bioavailability of IL-8, one of CXCR-2 ligands, with concomitant induction of tumor features in breast cancer cells." (PMID 38672477, 2024). "Targeting the CXCL7/CXCR2 pathway with a CXCR2 antagonist (SB265610) has been reported to decrease lung metastasis prevalence and reinforce CD8(+) CTLs in the spontaneous mammary tumors of MMTV-PyMT mice in chronic circadian disruption." (PMID 38505617, 2024). "SRGN exerts a regulatory role in the activation of IL-8/CXCR-2 and downstream signaling pathways in GBM and breast cancer cells." (PMID 38672477, 2024). "CXCR2 expression is also reduced in ER-negative and HER2-negative breast cancers, indicating a decrease in CXCL1 activity in these tumors and in tumor cells that have lost the expression of these receptors." (PMID 37108425, 2023). "Furthermore, elevated expression and signaling of CXCR2 is correlated with aggressive cancer phenotypes and a poor prognosis in various cancers, such as lung cancer, colorectal cancer, pancreatic cancer, prostate cancer, breast cancer, gastric cancer and squamous cell carcinoma." (PMID 36903345, 2023). "Collectively, these results indicated that CXCR2 blockade augmented chemotherapeutic effects of DTX, especially in CCL20high-expressing breast cancer patients." (PMID 36859354, 2023). "By blocking TGF-β signaling in combination with inhibition of the C-X-C motif chemokine receptor 2 (CXCR2), we reported a significant reduction in neutrophil migration toward TCM from the aggressive breast cancer cell line MCF10CA1a (M4)." (PMID 37682817, 2023).